TOMM7 (translocase of outer mitochondrial membrane 7)
Description:
Component of the translocase of the outer membrane of mitochondria (TOM) complex essential for the recognition and translocation of cytosolically synthesized mitochondrial preproteins. The TOM complex associates with the ion channel VDAC2 and PINK1 kinase at depolarized mitochondria, this interaction stabilizes PINK1 at the outer mitochondrial membrane and triggers downstream mitophagy by the recruitment of the E3 ubiquitin ligase PRKN.
Synonyms: TOM7; GMPGS
Tractability: Small molecule: a structure with a bound ligand is known. Antibody: UniProt predicts a signal peptide or a membrane-spanning region. PROTAC: ubiquitination databases record sites on it; its protein half-life has been measured.
Gene: Protein-coding gene on chromosome 7 (22,812,628 to 22,822,849, reverse strand). Ensembl gene ENSG00000196683.
Subcellular location: Mitochondrion outer membrane
Pathways (Reactome):
Autophagy: PINK1-PRKN Mediated Mitophagy
Protein localization: Mitochondrial protein import
Gene Ontology:
Molecular function: protein binding; protein transmembrane transporter activity
Biological process: positive regulation of establishment of protein localization to mitochondrion; positive regulation of type 2 mitophagy; regulation of protein stability; protein import into mitochondrial matrix; protein insertion into mitochondrial outer membrane
Cellular component: mitochondrial outer membrane translocase complex; mitochondrion; mitochondrial outer membrane; TOM complex
Genetic constraint (gnomAD): Loss-of-function variants: 7 observed, 8.11 expected, observed/expected ratio (o/e) 0.86, 90% interval 0.49 to 1.58. That is too few expected variants to judge how well the gene tolerates losing a copy. Missense variants: 70 observed, 62.85 expected, observed/expected ratio (o/e) 1.11, 90% interval 0.92 to 1.36. Synonymous variants: 26 observed, 22.05 expected, observed/expected ratio (o/e) 1.18, 90% interval 0.86 to 1.63.
Homologues: Orthologues: chimpanzee TOMM7 (98% identical), dog TOMM7 (98% identical), guinea pig TOMM7 (98% identical), macaque TOMM7 (98% identical), pig TOMM7 (98% identical), mouse Tomm7 (95% identical), rat Tomm7 (95% identical), tropical clawed frog tomm7 (84% identical).
Diseases named in the same sentence as TOMM7 in open-access papers:
TOMM7 is named in the same sentence as 19 diseases in open-access papers, as found by Europe PMC text mining. Sharing a sentence is not in itself a finding about the gene and the disease. The quoted sentences say what the papers report.
breast carcinoma (2 papers, 2017 to 2025). "We selected four genes (NOP10, OST4, SNRPG, TOMM7) known to be present in EVs from MCF-7 breast cancer cells overexpressing Rab27b-GFP11." (PMID 28577337, 2017). "TOMM7 is involved in mitochondrial protein import and may contribute to therapy resistance in breast cancer." (PMID 40618351, 2025).
Parkinson’s (2 papers, 2023 to 2024). "TOMM7 dominates cerebrovascular network homeostasis, and some studies have found that it is associated with the neurodegenerative disease Parkinson’s." (PMID 37372465, 2023).
type 2 diabetes (2 papers, 2022 to 2024). "Cerebral microvascular dysfunction caused by TOMM7 deficiency is the pathophysiological mechanism underlying the progression of type 2 diabetes-associated MCI and AD." (PMID 39452046, 2024). "A previous study confirmed a link between the TOMM7 gene and type 2 diabetes, in which genetic variation at the rs2240727 locus was associated with type 2 diabetes in the Chinese Dong population." (PMID 39452046, 2024). "We found potential genetic biomarkers for MCI in patients with type 2 diabetes using WGCNA combined with the LASSO algorithm and further screened four genes, COX7C, SNRPG, TOMM7, and RPS24, which are associated with the occurrence of type 2 diabetes." (PMID 39452046, 2024). "In addition, we verified that four of these genes (COX7C, SNRPG, TOMM7, and RPS24) are also able to predict the risk of type 2 diabetes and can be used as key genes in type 2 diabetes and MCI." (PMID 39452046, 2024). "The ROC curve was screened by integrating the GEO database, and revealed COX7C, SNRPG, TOMM7, and RPS24 as key genes in the progression of type 2 diabetes." (PMID 39452046, 2024). "The t-test results showed that the expression levels of four genes (COX7C, SNRPG, TOMM7, and RPS24) were significantly different between the type 2 diabetes and control groups (p < 0.05)." (PMID 39452046, 2024).
COVID-19 (1 paper, 2023). A disease caused by infection with severe acute respiratory syndrome coronavirus 2. "Nevertheless, we identified cases (for example, DR1, OAS1-3, TOMM7, MUC20) in which selection or archaic introgression contributed to changes in both SARS-CoV-2 immune responses and COVID-19 outcome." (PMID 37558883, 2023).
gastritis (1 paper, 2021). Inflammation of the stomach. "The capability of DGLA to attenuate LDL uptake and to improve mitochondrial biogenesis can be hypothesized to contribute to its activity against H. pylori-induced gastritis as various mitochondrial viability genes vital for mitophagy regulation (e.g., TOMM7) were downregulated in our analysis." (PMID 33717131, 2021).
hearing loss (1 paper, 2022). "Other genes were related to BPD-associated outcomes such as retinopathy of prematurity (ROP, e.g., GBP3, FJX1, HIPK2) and hearing loss (e.g., GJB6, TMEM63B) and mitochondrial energy metabolism (e.g., TOMM7, SLC25A26, SLC25A33, PDK1, PKM, MDH1)." (PMID 35484630, 2022).
hemorrhagic stroke (1 paper, 2025). A stroke caused by a bleed on the brain. "For instance, genes such as Gm11867, Gm10076, and Tomm7 were upregulated across multiple cell types in the model group, indicating an altered cellular response likely associated with post‐hemorrhagic stroke inflammation and neural damage." (PMID 41363028, 2025).
memory impairment (1 paper, 2023). "Finally, a correlation analysis found the memory impairment was positively correlated with the abnormal upregulation of Tomm7 but negatively correlated with decreased abundance of gut Alistipes_indistinctus, Lactobacillus_taiwanensis, Lactobacillus_paragasseri, and Lactobacillus johnsonii." (PMID 37362918, 2023).
TOMM7 also shares sentences with these, for which no sentence is quoted: cancer (2 papers); neurodegenerative disease (2); Obesity (2); alcohol-dependent (1); Cerebral ischemia (1); cerebrovascular disorder (1); infection (1); renal cell carcinoma (1); retinopathy of prematurity (1); tumor (1); uterine diseases (1).